PROS1 (protein S)
Diseases named in the same sentence as PROS1 in open-access papers (continued):
Sharing a sentence is not in itself a finding about the gene and the disease.
angina pectoris (2 papers, 2024 to 2025). The symptom of paroxysmal pain consequent to MYOCARDIAL ISCHEMIA usually of distinctive character, location and radiation. "High total protein S concentrations were also reported in patients with a history of angina pectoris and myocardial infarction." (PMID 38879576, 2024).
arterial disease (2 papers, 2021 to 2022). "The individuals from the arterial disease group compared to the control subjects showed additionally higher activity levels of factor IX and Protein S and slightly lower activity of factor XII." (PMID 35676710, 2022). "Therefore, as demonstrated by the analysis from the arterial disease group, levels of protein S may be elevated." (PMID 35676710, 2022).
arterial embolism (2 papers, 2021 to 2023). An arterial embolism occurs when a foreign substance or tissue mass gets lodged in an artery and obstructs the blood flow. "PE and splenic artery embolism were revealed by CTPA, and lab tests showed positive LA and aβ2GPI‐IgM, decreased protein C (36, normal 70–140), and protein S (49, normal 76–135) levels." (PMID 36658687, 2023).
Cerebral thrombosis (2 papers, 2023 to 2024). "Cerebral thrombosis is often the cause of neurological symptoms; thus, many different factors, including elevated levels of aPLs, homocysteine, fibrinogen, protein C, protein S, and antithrombin III, can be considered risk factors." (PMID 37605287, 2023).
esophageal squamous cell carcinoma (2 papers, 2001 to 2017). Esophageal squamous cell carcinoma (ESCC) is a type of esophageal carcinoma (EC) that can affect any part of the esophagus, but is usually located in the upper or middle third. "It is tempting to speculate that PROS1-driven AXL expression may lead to functional receptor heterodimerization with EGFR, as was shown for HNSCC and esophageal squamous cell carcinoma." (PMID 28118606, 2017).
hypercholesterolaemia (2 papers, 2013 to 2018). "Another patient revealed hypercholesterolemia and protein S deficiency." (PMID 23947749, 2013).
hyperuricemia (2 papers, 2023 to 2024). An abnormally high level of uric acid. "Additionally, the level of Gas6 and protein S in plasma of patients with hyperuricemia was significantly higher than that of healthy contrast group." (PMID 38066599, 2023).
Hypoglycemia (2 papers, 2019 to 2022). A decreased concentration of glucose in the blood. "As at hypoglycemia, %change of protein S remained lower at 24 h post-hypoglycemia in mild-hypo versus deep-hypo (-8.3 ± 6.4 vs. 3.3 ± 2.2%change at 24 h post-hypoglycemia, study-1 vs. study-2, p = 0.03)." (PMID 36203210, 2022). "By 24-hours, in controls, Protein S continued to show increased %change in response to deep-hypo and vWF continued to show increased %change in mild-hypo; plasminogen emerged at this timepoint as showing increased %change in milder prolonged hypoglycemia." (PMID 36203210, 2022). "From baseline to hypoglycemia, %change differences between studies were seen in PRPs for both T2D (PAI-1, CD40LG, GPVI, tissue factor) and controls (PAI-1, CD40LG, Protein S, vWF); two proteins being common (PAI-1, CD40LG)." (PMID 36203210, 2022).
Opportunistic infection (2 papers, 2013 to 2015). An infection that is caused by a pathogen that would generally not be able to cause an infection in a host with a normal immune system. "Although protein S deficiency is not correlated with HIV disease severity it appears that thrombosis is highly correlated with low CD4 counts, the presence of opportunistic infections, malignancies, or autoimmune disorders." (PMID 24570775, 2013).
Patent foramen ovale (2 papers, 2023). Failure of the foramen ovale to seal postnatally, leaving a potential conduit between the left and right cardiac atria. "There are a wide variety of causes for stroke in young adults such as hyperhomocysteinemia, illicit drug use, pregnancy, arterial dissections, patent foramen ovale (PFO), anti-phospholipid syndrome, malignancy, and protein S or C deficiency." (PMID 37273715, 2023).
pheochromocytoma (2 papers, 2020 to 2025). "The prothrombotic state observed in this case, including the decreased protein S activity and elevated ESR, is consistent with the inflammatory and catecholamine-driven changes associated with pheochromocytoma." (PMID 41357012, 2025). "By analogy, a pheochromocytoma that triggers high IL-6, or an acute-phase response, could lead to a similar decrease in protein S activity." (PMID 41357012, 2025). "Thus, pheochromocytoma may indirectly decrease protein S levels through cytokine-mediated acute-phase changes rather than a direct effect on protein S synthesis." (PMID 41357012, 2025).
primary immunodeficiency (2 papers, 2022 to 2023). "In the KEGG pathway analysis, several immune-related pathways were highly correlated with PROS1 expression, including Th17 cell differentiation, Th1 and Th2 cell differentiation, primary immunodeficiency, T-cell receptor signalling pathway, and natural killer (NK) cell-mediated cytotoxicity." (PMID 35879775, 2022).
thyrotoxicosis (2 papers, 2020 to 2025). A hypermetabolic syndrome caused by the elevation of thyroid hormone levels in the serum. "The low Protein S in our patient plausibly reflects an acquired deficiency linked to thyrotoxicosis, as described in mechanistic and clinical studies showing reductions in natural anticoagulants during hyperthyroidism with improvement after treatment." (PMID 41536381, 2025). "Therefore, the patient was diagnosed with massive PTE, thyrotoxicosis, and partial protein S deficiency." (PMID 32884835, 2020). "Laboratory testing demonstrated overt thyrotoxicosis with reduced Protein S levels, while Protein C, antithrombin III, autoimmune, and antiphospholipid panels were unremarkable." (PMID 41536381, 2025).
ulcerative colitis (2 papers, 2016 to 2023). An inflammatory bowel disease involving the mucosal surface of the large intestine and rectum. "Additionally, murine T cells lacking Pros1 became highly colitogenic when transplanted into Rag−/− mice, and Pros1 deficiency has been detected in patients with ulcerative colitis or Crohn’s disease." (PMID 27775650, 2016).
abortion (1 paper, 2024). the ending of pregnancy by removing a fetus or embryo before it can survive outside the uterus. "Among those genes, Sympk and Pros1 are involved in the regulation of signaling pathways associated with abortion." (PMID 38923264, 2024).
acromegaly (1 paper, 2024). Acromegaly is an acquired disorder related to excessive production of growth hormone (GH) and characterized by progressive somatic disfigurement (mainly involving the face and extremities) and systemic manifestations. "This study demonstrated that in comparison with controlled acromegaly and healthy subjects, patients with active acromegaly had higher values of cholesterol, triglyceride, low-density lipoprotein (LDL), very low-density lipoprotein (VLDL), fibrinogen, protein S, and fasting blood glucose." (PMID 37584889, 2024).
anaplastic meningioma (1 paper, 2013). A WHO grade III meningioma characterized by the presence of malignant morphologic features, including malignant cytology and a very high mitotic index (20 or more mitoses per ten high power fields). "Contrary to this, PROS1 seems to be downregulated in anaplastic meningiomas." (PMID 24358143, 2013).
atrophic gastritis (1 paper, 2020). "Further workup revealed isolated protein S deficiency and history of atrophic gastritis." (PMID 32534415, 2020).
Blindness (1 paper, 2019). Blindness is the condition of lacking visual perception defined as a profound reduction in visual perception. "One could speculate that PROS1 leaky mutations result in postnatal blindness in which residual activity of PROS1 suffices for proper function in all organs except the eyes." (PMID 32489947, 2019).
Cluster headache (1 paper, 2024). A type of headache characterized by repeated attacks of unilateral pain lasting 15 to 180 minutes and associated with local autonomic signs. "In addition, MERTK ligand galectin-3 was found at increased concentration in the serum of study participants with cluster headache, whereas the levels of MERTK ligands growth arrest specific 6 and protein S unaffected." (PMID 38783191, 2024).
coronary heart disease (1 paper, 2022). "The Second Northwick Park Heart Study, with a 14-year follow-up on 3052 middle-aged men, also confirmed that patients with higher protein S levels were associated with future risks of coronary heart disease." (PMID 36078892, 2022).
encephalitis (1 paper, 2022). An acute inflammatory process affecting the brain parenchyma. "A patient with a low protein S activity (45%—normal value 57–125%) and positivity for HLA A29 presented with bilateral ischemic maculopathy with encephalitis progression." (PMID 36560821, 2022).
experimental autoimmune encephalomyelitis (1 paper, 2020). An autoimmune demyelinating disease of the central nervous system that is produced experimentally in animals by the injection of homogenized brain or spinal cord in Freund's adjuvant. "During experimental autoimmune encephalomyelitis (EAE), the mRNA expression of MerTK, Gas6, and Axl significantly increase, whereas Tyro3 and ProS1 remain unchanged." (PMID 33121494, 2020).
gangrene (1 paper, 2021). Death of tissue, usually in considerable mass and generally associated with loss of vascular (nutritive) supply and followed by bacterial invasion and putrefaction. "In addition, switching to VKA in an acute HIT setting exposes the patient to a risk of warfarin-induced skin necrosis and gangrene due to the depletion of protein C and protein S." (PMID 35008518, 2021).
Graves disease (1 paper, 2025). Graves' disease is an autoimmune disorder that leads to overactivity of the thyroid gland (hyperthyroidism).It is caused by an abnormal immune system response that causes the thyroid gland to produce too much thyroid hormones. "Uncontrolled Graves’ disease can trigger a systemic hypercoagulable state with concurrent arterial and venous events, strengthened here by low Protein S and vessel-wall MRI features suggestive of inflammatory endothelialopathy." (PMID 41536381, 2025).
head and neck cancer (1 paper, 2019). A primary or metastatic malignant neoplasm affecting the head and neck. "In SCC-25 head and neck cancer cells expressing both Tyro3 and Axl, Western blotting showed that both natural TAM ligands ProS1 and Gas6 rapidly stimulated Tyro3 and Erk kinase phosphorylation, with ProS1 eliciting a greater effect." (PMID 31766614, 2019).
hepatitis C (1 paper, 2018). "Regarding his cortical vein thrombosis, again the role of hepatitis C and thepresence of low protein S levels cannot be disregarded." (PMID 29349091, 2018). "In our case, hepatitis C and low protein S levels could have contributed to ourpatient’s cerebral vein thrombosis; however, it may have just been anincidental finding." (PMID 29349091, 2018).
homocystinuria (1 paper, 2021). An autosomal recessive inherited metabolic disorder caused by mutations in the CBS, MTHFR, MTR, and MTRR genes. "Isolated cerebral venous thromboses require the search for an infectious cause, systemic lupus erythematous, and a procoagulant state (primary syndrome of antiphospholipids, protein S or C deficiency, and homocystinuria)." (PMID 33622338, 2021).
injury (1 paper, 2023). Damage inflicted on the body as the direct or indirect result of an external force, with or without disruption of structural continuity. "Similarly, Pros1 is a pro-neurogenic factor and neuroprotectant during ischemic-hypoxic brain injury." (PMID 37072781, 2023).
kidney cancer (1 paper, 2019). Primary or metastatic malignant neoplasm involving the kidney. "Conditioned medium from ProS1-secreting 786-0 kidney cancer cells replicated the kinase activation effects of recombinant ProS1 in SCC-25 cells, with specificity confirmed by ProS1 ligand traps and warfarin." (PMID 31766614, 2019). "A notable example was 786-0 kidney cancer cells, which showed high ProS1 expression but negligible Gas6 expression." (PMID 31766614, 2019). "Thus, we collected conditioned medium from 786-0 kidney cancer cells, which we had observed to express high levels of endogenous ProS1, which was added to SCC-25 cells as a responder system in experiments." (PMID 31766614, 2019).
lymph node metastasis (1 paper, 2025). "PTC patients with lymph node metastasis showed significantly lower IHC scores for PROS1 (P < .001), CLU (P = .003), and LRG1 (P < .001) than patients without metastasis, respectively." (PMID 40797389, 2025).
parathyroid adenoma (1 paper, 2020). "The protein S levels were lower and the fibrinogen levels higher in the patients with parathyroid adenoma." (PMID 33154484, 2020).
pelvic inflammatory disease (1 paper, 2014). Pelvic inflammatory disease (PID) is an acute or chronic inflammation in the pelvic cavity. "Hypercoagulable states, such as protein S deficiency and factor Leiden V mutation, surgery, cancer and pelvic inflammatory disease, were implicated as the possible predisposing factors for OVT." (PMID 25114685, 2014).
peripheral arterial disease (1 paper, 2022). A disorder of the arteries supplying the upper and lower extremity and the visceral organs. "Further work-up revealed elevated anti-phospholipid antibodies, anti-nuclear antibody, and D-dimer; low Protein S activity; and evidence of peripheral arterial disease on imaging studies." (PMID 36577976, 2022).
peritonitis (1 paper, 2018). Inflammation of the peritoneum (tissue that lines the abdominal wall and covers most of the organs in the abdomen). "While peritoneal PROS1 levels probably increase during the inflammatory phase of peritonitis, due to exudation of plasma proteins, it is unlikely that peritoneal PROS1 will remain at high levels in the absence of additional sources." (PMID 29545796, 2018). "Our findings now indicate that PROS1 is produced by macrophages during the resolution of murine peritonitis, and consequently its production and release by peritoneal macrophages as well as other cells contribute to peritoneal levels of PROS1." (PMID 29545796, 2018). "To investigate the role of PROS1 during the resolution of inflammation, we utilized the zymosan A-induced peritonitis as a prototypic model." (PMID 29545796, 2018). "To test the physiological role of PROS1 in resolution phase macrophages, we generated mice genetically ablated for Pros1 expression in the myeloid lineage and assessed macrophage efferocytosis and reprogramming in a model of zymosan A-induced peritonitis." (PMID 29545796, 2018).
Proteinuria (1 paper, 2015). Increased levels of protein in the urine. "Proteinuria may also explain the more pronounced elevation in D-Dimer levels in patients with severe renal dysfunction due to loss of important natural anticoagulant proteins, such as antithrombin, protein C and protein S, intensifying their hypercoagulability status." (PMID 26168189, 2015).
Retinal dystrophy (1 paper, 2013). Retinal dystrophy is an abnormality of the retina associated with a hereditary process. "MERTK is a receptor tyrosine kinase belonging to the TAM receptor family (Tyro-3, Axl, Mer), whose ligands include the vitamin K-dependent proteins growth arrest-specific protein 6 (gas6) and protein S, as well as the retinal dystrophy-gene products Tulp1 and Tubby." (PMID 23390493, 2013).
subarachnoid hemorrhage (1 paper, 2024). A serious neurological disorder characterized by intracranial hemorrhage into the subarachnoid space. "Protein S deficiency, a rare genetic disorder, can cause extensive CVT and related complications such as intracerebral and subarachnoid hemorrhage." (PMID 39268299, 2024).
Turner syndrome (1 paper, 2015). Turner syndrome is a chromosomal disorder associated with the complete or partial absence of an X chromosome. "In a study of 82 Turner syndrome individuals, 3.7% had protein C deficiency and 14.81% protein S deficiency and these percentages are higher than in the general population." (PMID 26579320, 2015). "As for the Turner syndrome per se, it is not generally considered as a condition that predisposes to thrombosis but there are data in the literature, which show low protein C values, low protein S values, and high fibrinogen concentration." (PMID 26579320, 2015).
uric acid stones (1 paper, 2013). "It was reported that prothrombin, protein Z, protein S and osteopontin were present in CaOx stones, but not in uric acid stones, indicating that these have essential roles in CaOx stone formation." (PMID 23874695, 2013).